HM13-IT1 (HM13 intronic transcript 1 )
Gene: Long non-coding RNA gene on chromosome 20 (31,563,166 to 31,564,076, forward strand). Ensembl gene ENSG00000235313.
Diseases named in the same sentence as HM13-IT1 in open-access papers:
HM13-IT1 is named in the same sentence as 5 diseases in open-access papers, as found by Europe PMC text mining. Sharing a sentence is not in itself a finding about the gene and the disease.
HM13-IT1 shares sentences with these, for which no sentence is quoted: cancer (1 paper); colon cancer (1); endometrial cancer (1); gastric cancer (1); lung carcinoma (1).